EGFR (epidermal growth factor receptor)
Diseases named in the same sentence as EGFR in open-access papers (continued):
Sharing a sentence is not in itself a finding about the gene and the disease.
tumor (continued). "In the cases with amplification, fluorescence in situ hybridization for HER2 verified gene amplification and immunohistochemistry for HER2, EGFR and CCNE1 verified the overexpression of proteins in tumor cells." (PMID 25372287, 2014). "Here, the combined EGFR and Notch inhibition decreases significantly the AKT activation and thus suppresses tumor growth more effectively." (PMID 24864230, 2014). "We first showed that the EGFR GCN as analyzed by silver in situ hybridization (SISH) positively correlated with immunohistochemistry (IHC), when the evaluation was performed from tumor areas of highest staining intensity." (PMID 24940619, 2014). "Lapatinib showed inhibition of cell growth following dephosphorylation of EGFR, HER2, AKT, and inhibited tumor xenograft growth of the HN5 and BT474 cells in mice." (PMID 25110867, 2014). "SKOV3 xenografts, over-expressing HER2, EGFR, HER3, and HER4 exhibited an average tumor growth delay that ranged from 17.1 days (15 mg/kg) to 41.2 days (30 mg/kg) after treatment with dacomitinib and complete tumor regressions at doses as low as 15 mg/kg." (PMID 25110867, 2014). "Copy number alterations in EGFR, CDKN2A/B/p14ARF were considered early events because all tumor samples shared these changes." (PMID 25411563, 2014). "In vitro and in vivo tumor models have also demonstrated direct interactions between IGF-1R, EGFR/HER-2, and co-localization of IGF-1R and HER-2." (PMID 25424625, 2014). "In the EGFR-positive tumor sample, FISH revealed that the majority of the cells were expressing EGFR." (PMID 25013472, 2014). "Previous studies have reported that IFNA-expressing tumor cells enhance generation and promote survival of tumor-specific cytotoxic T lymphocytes and that IFNA improves the anti-proliferative effect of EGFR inhibitors in CRC cell lines." (PMID 25350395, 2014). "IHC staining fractions for CA9, EGFR, MCT4, pAKT, GLUT1 and PIMO, as well as the BrdU LI, VD and PF of the microscopy-imaged tumor sections were analyzed." (PMID 24571588, 2014). "Using this model we demonstrate how anti-tumor activity of M1-like macrophages and M2-like macrophages can be induced by bacterial stimuli like L-MTP-PE and the therapeutic anti-EGFR antibody cetuximab, respectively." (PMID 24612598, 2014). "Four human tumor cell lines were analyzed for their proliferation and survival capacity upon anti-SphK1 targeting with the highly specific SKI-II inhibitor and anti-EGFR targeting with cetuximab." (PMID 25245676, 2014). "Notwithstanding, proteolytic enzyme urokinase plasminogen activator is upregulated after irradiation in the IOMM-Lee meningioma cells via activation of EGFR, MEK1/2, and p38 signaling pathways, which results in increased tumor invasion and migration in vitro." (PMID 25302298, 2014). "Oral administration of KPT-276 significantly inhibited tumor xenograft growth in H1975-bearing NOD-SCID mice, which were resistant to EGFR-TKI treatment." (PMID 24595136, 2014). "The correlation of AMPK activation and EGFR expression was seen in HNSCC cells and human tumor specimens." (PMID 24457597, 2014). "Finally, our results suggested that the role of EGFR amplification in cancer progression might not be directly linked to the histological tumor grade." (PMID 24885034, 2014). "Upstream signaling molecules EGFR can stimulate phosphorylation of AKT, activate cellular pathways, and promote tumor cell growth, proliferation, invasion and metastasis." (PMID 25000529, 2014). "In a general manner, overexpression of EGFR and HER2 in tumor cells has been correlatedwith poor prognosis." (PMID 25004291, 2014).
tumor (continued). "We showed that the antagonist HM90822B efficiently downregulates XIAP and survivin in human EGFR-overexpressing NSCLC cells and demonstrated that this downregulation contributes to enhance cell cycle arrest and apoptosis, even to regress tumor growth in vivo." (PMID 25321484, 2014). "The current study demonstrated the anti-tumor effects of KPT-185 in NSCLC cells, including EGFR-TKI-resistant NSCLC cell lines." (PMID 24595136, 2014). "SH3KBP1 has been implicated in cell death and shown to mediate down regulation of EGFR, and JUND has been shown to reduce tumor angiogenesis." (PMID 24550933, 2014). "After drugs, such as EGFR-TKI, kill sensitive tumor cells, drug-resistant tumor cells are selected in the treatment." (PMID 25610713, 2014). "If HOS-143b cells were coated with the anti-EGFR antibody cetuximab, the percentage of CD32+CFSE+ macrophages was increased, indicative for cell conjugate formation between macrophages and tumor cells." (PMID 24612598, 2014). "Because most GBM express EGFR and since HIF1α is a marker gene upregulated upon hypoxia in GBM, proscillaridin A likely influences GBM tumor growth via various mechanisms." (PMID 25400117, 2014). "The epidermal growth factor receptor (EGFR) is a tyrosine kinase that is expressed in normal tissue and in tumor cells." (PMID 25120668, 2014). "LRIG1 negatively regulates multiple receptor tyrosine kinases signaling including the epidermal growth factor receptor (EGFR) and is a proposed tumor suppressor." (PMID 25353163, 2014). "Accordingly, lapatinib, an EGFR/HER2 tyrosine kinase inhibitor, as well as metformin, reduced the tumor growth of cells overexpressing NTS and NTSR1." (PMID 25249538, 2014). "In cases with amplification, IHC for HER2, EGFR and CCNE1 showed overexpression of proteins in the tumor cells." (PMID 25372287, 2014). "Akt is involved in cell survival and proliferation in various tumor types and can be phosphorylated and activated through several signaling pathways, including MAPK and EGFR signaling." (PMID 25321484, 2014). "The present study has focused on EGFR since it was previously identified as a critical target of miR-7 in many solid tumors, including NSCLC, and it contributes to tumor progression and poor prognosis." (PMID 25289099, 2014). "The results are thus in agreement with our clinical data indicating that both EGFR GCN and KRAS status define the tumor cell response to anti-EGFR mAbs." (PMID 24940619, 2014). "After chemotherapy, the patients were retreated with EGFR-TKI (gefitinib 250 mg qd or erlotinib 150 mg qd), and the tumor progression was observed." (PMID 25610713, 2014). "Intrinsic tumor subtypes, defined by a panel of IHC markers (ER, PR, HER2, CK5, CK6, EGFR), identified 51% luminal A, 16% luminal B, 21% basal-like, 6% HER2+/HR-, and 6% unclassified." (PMID 25287138, 2014). "A number of groups, including our own, observed highly activated EGFR, Akt and Erk signaling pathways in human NSCLC tumours." (PMID 24456610, 2014). "Notably, EGFR signalling has also been found to regulate E-cadherin expression and function in tumour cells through inhibiting its transcription and promoting its cleavage, degradation and endocytosis, suggesting a feedback regulation between E-cadherin and EGFR signalling." (PMID 25164084, 2014). "In conclusion, high dose CUR inhibited tumor growth and angiogenesis in CaSki-implanted mice probably mediated by the downregulation of VEGF, COX-2 and EGFR." (PMID 24860830, 2014).
tumor (continued). "Given the pivotal roles the oncogenic STAT3 and EGFR pathways play in tumor development, we focused primarily on the repertoire of interleukin-6-like STAT3 activators and EGFR agonists secreted by tumor-primed monocytes and MΦ." (PMID 23597096, 2013). "Overexpression of epidermal growth factor receptor (EGFR) has been observed frequently in a large subset of CUP and gefitinib is effective in a broad spectrum of tumor types." (PMID 24137395, 2013). "In consistence with our findings, dysregulated miR-7 is recently detected in tumor tissues from HCC patients and functions in suppressing cell growth by targeting Akt/mTOR, a survival signaling pathway downstream of EGFR." (PMID 23840262, 2013). "Although not statistically significant, the frequency of EGFR mutations was higher in Chinese (46.4%), in patients aged less than or equal to 60 years old (48.8%), in advanced stage patients (45.8%), in moderately differentiated tumour cells (47.6%), and in never smokers (68%)." (PMID 23590575, 2013). "Nuclear localization of CCN, EGF/EGFR and FGF/FGFR is often detected in cancer cells, in correlation with tumor progression." (PMID 24340049, 2013). "c-MET is considered a possible therapeutic target in numerous tumor types and is also a candidate regulator of response to anti-HER2 and anti-epidermal growth factor receptor (EGFR) therapy." (PMID 23251249, 2013). "ErbB family member genes (ERBB-genes; EGFR, ERBB2, and ERBB3) and 15 previously reported tumour suppressor candidate genes (TS-genes) were next studied by heat maps in all four data sets." (PMID 23835063, 2013). "H1299 EGFR tumor had lower morpholino-[124I]IPQA accumulation and produced similar images before and after treatment with EGFR inhibitor, Gefitinib (Iressa)." (PMID 23956990, 2013). "In conclusion, given that a woman experienced a recurrence after a primary DCIS, tumor markers related to a recurrence being invasive compared to a new in situ were ER+, HER2−, and EGFR−." (PMID 24490077, 2013). "Results from completed phase I/II clinical trials with epidermal growth factor receptor (EGFR) monoclonal antibodies, tumor cell, or dendritic cell (DC) vaccines were encouraging, demonstrating disease stabilization, and prolonged patient survival." (PMID 24273748, 2013). "Epidermal growth factor receptor (EGFR) is a key factor in epithelial malignancies, and its activity enhances tumor growth, invasion, and metastasis." (PMID 23986907, 2013). "The molecular mechanism responsible for this elevated expression of EMMPRIN in co-cultures remains unknown, although EGFR and angiotensin II were implicated in its expression in fibroblasts and macrophages, respectively, but not in tumor cells." (PMID 23874303, 2013). "This priming process induces secretory patterns that consistently feed back to activate oncogenic EGFR- and STAT3 pathways in tumor cells." (PMID 23597096, 2013). "Here we report that although EGFR/ERK pathway inhibition initially attenuates tumor progression and induces tumor regression, it is uniformly limited by an acquired drug resistance, and subsequent failure to sustain either tumor regression or stability." (PMID 23342981, 2013). "EGFR is greatly expressed in HGG patients and gene amplification represents one of the most frequent alterations in this tumor type." (PMID 23782513, 2013). "In our study, these effects of gefitinib were confirmed by the phospho-EGFR assay and analysis of 3H-FLT uptake in the tumor." (PMID 24191959, 2013). "Tumor-primed PBMC and MΦ secrete one specific EGFR agonist, respectively, in combination with OSM, the relevant STAT3 activator." (PMID 23597096, 2013). "Rational choice of tumor target antigen will help optimize the efficacy of scFv:TRAIL-based therapeutics, as evidenced by a study using an EGFR-blocking antibody fragment." (PMID 23840967, 2013).
tumor (continued). "Expression and activation of epidermal growth factor receptor (EGFR) is increased in colonic precancerous lesions and tumours, thus EGFR is considered a tumour promoter." (PMID 23457600, 2013). "We identify HB-EGF and OSM as the key EGFR and STAT3 activators secreted by tumor-primed MΦ, and EREG and OSM as the key activating factors secreted by tumor-primed PBMC." (PMID 23597096, 2013). "Several targeted liposomes have shown increased efficacy compared to non-targeted liposomes despite identical EPR-driven levels of tumor accumulation, including the antibody-targeted anti-HER2 and anti-EGFR formulations of liposomal doxorubicin." (PMID 24009717, 2013). "Given the strong correlation with EGFR expression, it is conceivable that EGF signalling induces ZEB1 in these tumours." (PMID 23818228, 2013). "Theoretically, the EGFR/CD3 BsAb binds to EGFR and CD3 simultaneously, so it should not only activate T cells/CIK cells, but also restrict tumor cell growth." (PMID 23833649, 2013). "For example, the erlotinib-resistant tumor PANC420 expressed markedly higher Mig6 than the erlotinib-sensitive tumor PANC410, even though they expressed comparable amounts of EGFR protein." (PMID 23935914, 2013). "Previous reports have shown that TAMs contribute to tumor progression through secretion EGF and upregulation of the EGFR/Stat3/Sox-2 signaling pathway." (PMID 24312366, 2013). "The univariate analysis data showed that tumor size, pathological tumor stage, positive lymph nodes, tumor-node-metastasis (TNM) stage (UICC, sixth or seventh edition), and EGFR expression all affected the OS and DFS of the patients." (PMID 24131756, 2013). "We conclude that the ERBB-profile (high expression of EGFR, ERBB2 and ERBB3) defines a ganglion-rich neuroblastic tumour sub-set." (PMID 23835063, 2013). "Since hypoxic tumor regions are typically resistant to current therapy, this emphasizes the potential of DDX3 inhibitors, perhaps in combination with HER2 and/or EGFR inhibitors." (PMID 23696831, 2013). "In ER+ tumours from postmenopausal women, NRG1 levels correlated positively with EGFR/HER1 (r=0.606, P=0.002) and negatively to ESR1 (r=-0.769, P=0.003) and E2 levels (r=-0.542, P=0.020)." (PMID 23991224, 2013). "Specifically, we find that the presence of EGFR and HER2 in specific tumor subtypes corresponds with distinct expression and localization of CARM1, suggesting potential interactions between CARM1 and these hormone receptors." (PMID 23663560, 2013). "The mRNA expression levels of all analysed genes were found to be log normally distributed except for EGFR/HER1 in normal tissue and HER4 in tumour tissue that were found to be normally distributed." (PMID 23991224, 2013). "We examined growth and immune signalling proteins such as EGFR, HSPA8 and cytokines IL-6 that are involved in the survival of tumor." (PMID 23414419, 2013). "Newly developed drugs and epidermal growth factor receptor (EGFR) tyrosine kinase inhibitors (TKIs) have been shown to affect treatment outcome, depending on the histological tumor type." (PMID 24649230, 2013). "Besides EGFR expression levels, other factors, such as EGFR mutations, tumor microenvironment, tumor vasculature density and permeability, tumor interstitial pressure, pharmacokinetics, and tumor penetration ability of compounds, could influence anti-EGFR treatments." (PMID 23748900, 2013). "Higher uptake of 60Cu-ATSM has been shown to correlate with other biomarkers of tumor hypoxia such as vascular endothelial growth factor receptor (VEGF), epidermal growth factor receptor (EGFR), cycloxygenase-2, and carbonic anhydrase-IV." (PMID 23549376, 2013). "Our work describes pro-tumorigenic marker proteins that identify tumor-supportive mononuclear cells and establishes a basis for therapeutic intervention aimed at neutralising these STAT3 and EGFR activators at the molecular level." (PMID 23597096, 2013).
tumor (continued). "To identify tumor proliferation and apoptosis following i.p. injections with LPEI-complexed EGFR specific siRNA, we also examined PCNA expression and apoptosis-induced DNA fragmentation in mice xenografts." (PMID 27234384, 2013). "In conclusion, this is the first study to demonstrate that LPS effectively induces tumor growth in various experimental models of NSCLC in vitro, ex vivo and in vivo via CD14-, TLR4-, EGFR- and COX-2-signaling." (PMID 22923191, 2013). "It has been shown, however, that combination of anti-EGFR antibodies, namely cetuximab and nimotuzumab with radiotherapy reduces the number of CD133-positive tumor initiating cells." (PMID 23637683, 2013). "Additional support has been provided in a recent study showing that the invasive areas of GBMs with co-amplification of EGFR and PDGFR exclusively contain EGFR-amplified cells, while PDGFR amplified cells are only found in the main tumor mass." (PMID 23429996, 2013). "Recent studies indicated that LDP itself, the apoprotein of LDM, shows binding capability to a spectrum of human tissues, and notably that the binding capability correlates with the overexpression of EGFR and HER2 on the tumor tissue microarray." (PMID 24128285, 2013). "EGFR activation regulates PKM2 functions in a subcellular compartment-dependent manner and promotes gene transcription and tumor growth." (PMID 23840737, 2013). "Subsequent to priming with tumor cell-secreted factors, human primary MΦ and peripheral blood monocytes (PBMC) both secrete OSM, but each cell type in combination with one specific EGFR agonist." (PMID 23597096, 2013). "Notably, GBMs often contain stably mosaic cellular compositions, including the concomitant presence of tumor cell subsets with and without EGFRvIII mutation, or co-existing tumor micro-regions harboring cell subpopulations with oncogenic amplifications of either EGFR or PDGFR genes." (PMID 23508692, 2013). "Because they presented the highest phospho-EGFR expression levels, along with high expression levels for phospho-AKT and phospho-MEK1, TCG2, TCG3 and TCG4 tumor lines were expected to benefit from gefitinib-based treatment." (PMID 23874590, 2013). "It was found that HGF induced resistance to reversible, irreversible, and even mutant-selective EGFR-TKIs by restoring MetGab1/PI3K/Akt pathway, indicating that HGF is an important therapeutic target for overcoming tumor resistance to EGFR-TKIs." (PMID 23533466, 2013). "ZEB1 positive tumours showed a significant enrichment for PCNA and EGFR, while NF1 deletions were significantly more prevalent in ZEB1 negative specimens." (PMID 23818228, 2013). "This study was designed to assess “in situ” the biologic activity of the EGFR TKI, and gefitinib reached enough tumor concentrations to inhibit EGFR activation, however, this was not translated into clinical benefit." (PMID 24216699, 2013). "COX-2 expression has been shown to upregulate the EGFR, PI3K/Akt and ERK signaling, thereby induce tumor cell proliferation, migration and invasion." (PMID 23737956, 2013). "There have been several studies correlating various imaging features such as tumor border, enhancement pattern, peritumoral edema, multiplicity, T2 signal and intratumoral cystic change with genetic profiles of GBM, including EGFR and MGMT expression." (PMID 23977117, 2013). "Our data show that co-targeting EGFR and IGF-1R plus irradiation significantly reduced S phase and arrest cells at G0/G1 phase in MDA-MB-468 cells, profound tumor cell kill was observed, therefore, the cells were sensitized to irradiation." (PMID 23777562, 2013). "Epidermal growth factor receptor (EGFR) is involved in the development of many human malignant tumors and plays an important role in tumor growth and metastasis." (PMID 23496982, 2013).